CRH (corticotropin releasing hormone)
Diseases named in the same sentence as CRH in open-access papers (continued):
Sharing a sentence is not in itself a finding about the gene and the disease.
Anxiety (continued). "Maternal stress and anxiety increase the levels of corticotropin-releasing hormone (CRH) in the placenta, which in turn affects the incidence of preterm birth and many other related maternal and neonatal complications." (PMID 37629614, 2023). "We show that tumor-bearing mice exhibited significant anxiety-like behaviors and that corticotropin-releasing hormone (CRH) neurons in the central medial amygdala (CeM) were activated." (PMID 37847562, 2023). "Our previous studies also showed that moxibustion can relieve anxiety in colitis mice by reducing the secretion of corticotropin-releasing hormone in the hypothalamus." (PMID 36819717, 2023). "CRH also modulates behavioral activities concerning anxiety, mood, arousal, locomotion, reward, and feeding, and increases sympathetic activation." (PMID 37058223, 2023). "Localized injection of CRH into the medial prefrontal cortex significantly increased anxiety-related behavior in the PMT." (PMID 36230412, 2022). "In transgenic animal models, overexpression of ACE2 in the brain leads to decreased anxiety via the reduction of plasma corticosterone, CRH in the hypothalamus, and pituitary-expressed proopiomelanocortin." (PMID 34648616, 2022). "It is well-documented that CRH activates prefrontal excitatory neurons and mediates depressive- and anxiety-like behaviors." (PMID 35280164, 2022). "Choi and colleagues observed increased anxiety-related responses in zebrafish and mouse sam2 knockout models and found sam2 repressed Corticotropin-releasing hormone (crh) expression and thus the HPA axis." (PMID 35574490, 2022). "Loss of ACE2 in the hypothalamus causes alterations in corticotropin-releasing hormone (CRH), thereby affecting the stress response and anxiety-related behavior." (PMID 34648616, 2022). "Increased CRH levels, induced by glucocorticoids, have permanent effects, especially on the amygdala development and function, leading to anxiety problems in children." (PMID 35740747, 2022). "In the current study, the serum levels of BDNF and CRH with respect to depression and anxiety scores in vitiligo patients and control subjects were compared." (PMID 35508633, 2022). "In the CeA, CRH plays an important role in stress-adaptive responses, mediating stress-induced anxiety-like behaviour through projections to the dorsolateral part of the bed nucleus of the stria terminalis." (PMID 35880052, 2022). "When the human body is stimulated by anxiety, CRH can enter the anterior pituitary in the blood of the portal system and stimulate it to release ACTH, resulting in an increase in CORT secretion." (PMID 35186098, 2022). "Researchers also found that purified SAM2 protein increased inhibitory postsynaptic transmission to corticotropin-releasing hormone (CRH) neurons in the paraventricular nucleus, which is involved in stress and anxiety responses." (PMID 35409306, 2022). "Stimulation of brain NMUR2 has been found to modulate anxiety-like behaviour and trigger stress-related molecular events by CRH exocytosis." (PMID 35631458, 2022). "A subpopulation of serotonergic neurons in raphe nuclei respond to an elevation of corticotropin-releasing hormone (CRH) and believed to be associated with anxiety-like behavior in rats." (PMID 35573988, 2022). "Previous research has also found that immediate sucrose rewards can alleviate anxiety-like behavior during acute stress and inhibit paraventricular corticotropin-releasing hormone (CRH) neurons." (PMID 36614104, 2022). "Hormones have been demonstrated to affect neuropeptides involved in stress and anxiety, like oxytocin and corticotropin-releasing hormone (CRH)." (PMID 35444632, 2022). "In a stressful situation, which evokes the activation of the HPI axis and the action of the corticotropin-releasing hormone (CRH) cascade, culminating with cortisol release, zebrafish response is consistent with an anxiety-like behavior." (PMID 35743088, 2022).
Anxiety (continued). "Our results show increased Crh and Crhr1 (but not Crhr2) gene expression in the CeA in FD rats, supporting a potential role for augmented CRH signaling in the pathogenesis of depression and anxiety in this model." (PMID 33591956, 2021). "Psychologic functioning also interacts with the endocrinologic system as anxiety can trigger a stress response initiated by corticotropin-releasing hormone (CRH) release." (PMID 34208479, 2021). "It has, indeed, been demonstrated that anxiety-like behaviors dependent on CRH cells rather relies on an excitatory glutamatergic projection to a subset of neurons in the perifornical region of the lateral hypothalamus than on endocrine signaling." (PMID 33005029, 2021). "CRH is primarily in the hypothalamus and amygdala, and transduces activation of the hypothalamic–pituitary–adrenal axis, while amygdala CRH transduces anxiety and conditioned fear." (PMID 34502154, 2021). "Van Gaalen M., Stenzel-Poore M., Holsboer F., Steckler T. Effects oftransgenic overproduction of CRH on anxiety-like behaviour." (PMID 34901719, 2021). "The amygdala CRH system induces anxiety, but also activates the hypothalamic CRH system and the LC-NE system." (PMID 34177605, 2021). "Because there are so many neurotransmitters and receptors that are connected to CRH signaling, targeting CRH and the CRHRs presents a potential avenue to cover a broad array of pathways in the treatment of anxiety, mood, and substance use disorders." (PMID 33867924, 2021). "Administration of the peptidergic CRH antagonist α-helical CRH suppresses stress-induced colonic motility, visceral pain, and anxiety in IBS patients." (PMID 33538894, 2021). "CRH infusion to the BST was found to increase anxiety-like behavior in rats in the elevated plus maze (EPM) test, an effect mediated through CRHR1s." (PMID 33867924, 2021). "Conversely, serotonergicprojections from DR to CRH neurons in BNST promote thedevelopment of anxiety through 5-HT2C receptors activation." (PMID 34901719, 2021). "The link between the BST and maladaptive behaviors beyond anxiety is an emerging field of research, and CRH signaling within the BST presents new treatment targets for these behaviors." (PMID 33867924, 2021). "Chemogenetic activation or inhibition of CeA CRH neurons bidirectionally modulates anxiety-like behavior, and mediates conditioned flight." (PMID 34642456, 2021). "Direct CRH neurons activationin the nucleus ovale of the BNST induces the anxiety that occurs after chronic stress." (PMID 34901719, 2021). "Meanwhile, CeA CRH neurons exerted pro- or antinociceptive effects depending on the type of CRH receptors, which is well known to be related to anxiety-like behaviors." (PMID 33428940, 2021). "Along with CRH hypersecretion in melancholia, these lead to further anxiety and arousal, decreased sleep, and decreased food intake and sexual activity." (PMID 34502154, 2021). "We found that, in WT females, MS induced a reduction in anxiety and a concomitant significant decrease in the activation of CRH neurons in the Pa, upon exposure to the EPM." (PMID 34895132, 2021). "Prior work examining the effects of repeated exposure to alcohol in adolescence on the gene expression of critical regulators of stress and anxiety likewise reported increased CRH gene expression in the PVN in human males." (PMID 34572345, 2021). "The potential role for CRH in the pathophysiology of anxiety disorders was extensively studied, therefore proposing further research on the effects of anti-anxiety agents on CRH neurotransmission." (PMID 32499732, 2020). "The central role for CRH in stress signaling (either related to fear or anxiety) highlights it as potential therapeutic target for stress-related diseases, including anxiety disorders." (PMID 29904149, 2020).
Anxiety (continued). "The corticotropin-releasing hormone (CRH) system has received considerable attention as a promising therapeutic target for anxiety and stress-related disorders." (PMID 32694970, 2020). "Although in both conditions variable results for cortisol concentration in circulation have been reported, anxiety generally involves increased CRH and/or GR expression levels and enhanced Dex suppression (denoting enhanced negative central feedback)." (PMID 32298279, 2020). "Despite a growing body of evidence reporting the impact of ELS on anxiety-like behavior and its relation with CRH expression, there are still challenges to improve the translational impact of ELS animal models." (PMID 33304248, 2020). "On the other hand, another Gαq protein-coupled receptor is 5-HT2C serotonin receptors deleted mice exhibit the anxiolytic phenotype through a selective blunting of BNST corticotropin-releasing hormone neuronal activation in response to anxiety stimuli." (PMID 33263080, 2020). "Women with perceived symptoms of anxiety and depression during pregnancy had altered expression patterns for CRH, HSD11B2, and AVP genes in the placentas, compared to the control population." (PMID 32752005, 2020). "With the decreased expression of CRF1R in the amygdala, the globus pallidus lateralis projection by CRH neurons in the amygdala decreased, which increased the response to stress and reduced the anxiety levels." (PMID 32489558, 2020). "GR upregulates corticotropin-releasing hormone (CRH) expression in the central amygdala (CeA), which modulates anxiety-like behavior and memory." (PMID 32449767, 2020). "In high anxiety settings, this effect is overridden by direct local GABAergic inhibition between CEl CRH+ and CEl SOM+ cells." (PMID 29904149, 2020). "In particular, these data demonstrated that acute neonatal nociception affects early-life amygdala CRH mRNA expression in a sex dependent manner and reduced juvenile innate anxiety." (PMID 31601633, 2019). "It is in line with the evidence that longer staying with ambivalence attenuates the neural circuit activity involved in controlling anxiety, and also in a way justifies the CRH regulation of anxiety." (PMID 30898126, 2019). "Overall, neonatal pain drives CRH expression and produces behavioral changes in anxiety that persist until the juvenile stage." (PMID 31601633, 2019). "Some studies have confirmed that the excessive activation of the HPA axis with a mass secretion of CRH is an important biological basis for pathological anxiety." (PMID 30881446, 2019). "Allopregnanolone treatment also decreased CRH mRNA expression in the PVN and CRH-induced anxiety-like behaviors." (PMID 30906252, 2019). "Overexpression of CRH has repeatedly been shown to induce stress-like behavioral responses including increased fear and anxiety under baseline conditions." (PMID 31619956, 2019). "Several studies have suggested that CRH plays a vital role in the occurrence of anxiety, as a major transmitter for stress response in the HPA axis." (PMID 30881446, 2019). "CRH has repeatedly been identified as an important contributor to fear and anxiety behavior and is largely expressed in stress-related brain regions, including the amygdala and BNST." (PMID 31379626, 2019). "Further study is needed to identify the processes that explain anxiety-related behaviors in asthma, particularly role of hormonal alterations, such as the CRH-ACTH-cortisol system – this can be another piece of puzzle." (PMID 31863052, 2019). "Specifically, stimulation of CRH+ CeA-LC terminals increases activity in LC and drives anxiety-like behaviors through type 1 CRH receptor (CRH1R) activation." (PMID 31467945, 2019). "It should be noted that a similar behavioral profile with increased innate fear/anxiety and reduced learned (conditioned) fear has been observed in a transgenic mouse overproducing corticotropin-releasing hormone." (PMID 30760981, 2018).
Anxiety (continued). "CNP's effects on anxiety are dependent on corticotropin releasing hormone and medial prefrontal cortex, hippocampus and other limbic system structures participate in regulation of the hypothalamo-pituitary adrenal axis." (PMID 30072880, 2018). "VP and CRH can amplify the effects of each other on aggression and anxiety, especially during circumstances involving intense challenges." (PMID 29312146, 2017). "VP, in the context of other centrally active molecules, such as CRH, dopamine, and serotonin, regulates emotional states, including anxiety." (PMID 29312146, 2017). "Higher anxiety- and depression-like behaviours and elevated gene expression of hypothalamic corticotropin-releasing hormone and hippocampal serotonin receptor subtypes were observed in subordinate mice compared with those of dominant mice." (PMID 28765614, 2017). "Corticotropin-releasing hormone (CRH), with widespread expression in the brain, plays a key role in modulating a series of behaviors, including anxiety, arousal, motor function, learning and memory." (PMID 28790896, 2017). "CRH receptors within the bed nucleus of the stria terminalis (BNST) are known to mediate the effects of CRH on anxiety-like behavior." (PMID 26318631, 2015). "The amygdala CRH system is largely responsible for the activation of anxiety and fear related behaviors, and CRH antagonists given ICV or systemically block fear conditioning." (PMID 25878903, 2015). "The central CRH system plays a major role in the regulation of anxiety-like behavior, particularly at the level of the amygdala." (PMID 26318631, 2015). "Human genetic studies implicate the CRH pathway in mediating anxiety and depression symptoms, and knockout studies have shown that Crhbp deletion impairs aspects of maternal care in mice." (PMID 24765068, 2014). "The critical role of CRH-mediated circuits has been demonstrated in diverse experiments, which have revealed that the activation of CRH circuits elicits behavioral responses that are typically observed during states of fear or anxiety." (PMID 23913254, 2014). "An animal study has demonstrated that rikkunshito attenuates the activities of corticotropin-releasing hormone (CRH)-producing neurons and reduces anxiety-like behavior in tumor-bearing rats." (PMID 24447839, 2014). "It counteracts anxiogenic effects of CRH in several brain regions that regulate stress and anxiety, including the hypothalamus, hippocampus, amygdala, and locus coeruleus." (PMID 23422934, 2013). "In support the role of CRH in withdrawal anxiety and anorexia it has been recently shown that CRF-1 receptor antagonists CP154526 and antalarmin reduced weight loss and irritability during naloxone precipitated morphine withdrawal in rats." (PMID 23805290, 2013). "Regional-specific expression and signalling capacity of CRH and its receptors has implications for anxiety and depression disorders." (PMID 23483921, 2013). "Some studies have demonstrated that ICV CRH increases locomotion, anxiety, fear, despair, and emotionality, decreases food intake, sexual activity, exploration and social interaction and activates the HPA axis and the autonomic nervous system." (PMID 23077729, 2012). "We have previously shown that repeated binge-pattern alcohol exposure increased the expression of two critical central regulators of stress and anxiety, corticotrophin-releasing hormone (CRH) and arginine vasopressin (AVP), in adolescent male rats." (PMID 22384198, 2012). "A separate study also shows that overexpressing CRH in forebrain glutamatergic neurons (Crh-COECamCreERT2) of mice increases anxiety in the EPM and LD tests, while anxiolysis is observed in the absence of forebrain CRH-R1." (PMID 23077729, 2012). "Although the sample sizes in these studies are relatively small and there exist potential for Type I or Type II errors, they demonstrate an important role for the CRH gene in mediating anxiety-like behaviors in humans." (PMID 23077729, 2012).
Anxiety (continued). "The authors presented that chronic (4-month) overexpression of CRH in the CeA of male mice under basal conditions had minor effects on anxiety in the OF and LD preference tests." (PMID 23077729, 2012). "CRH activity through CRH-R1 receptors, therefore, not only mediates anxiety behaviors but functions in hippocampus-dependent cognitive performance." (PMID 23077729, 2012). "Comparatively, when this approach was used to knockdown CeA CRH, mice show decreased anxiety in the EPM." (PMID 23077729, 2012). "HPA system activation with increased levels of cortisol and corticotropin releasing hormone have also been suggested to play a role in depressive symptoms and in mediating inflammatory effects on mood and anxiety." (PMID 22164271, 2011). "CRH, a key hormone operating in concert with catecholamines and other neuotransmitters plays a pivotal part in the control of anxiety-like behavior in rodents and humans." (PMID 21869897, 2011). "Prenatal stress similarly programmes increased anxiety-related behaviours with elevated CRH in the amygdala as well as schizophrenic-like behaviour which can be reversed by administration of oxytocin into the central amygdala." (PMID 21144857, 2011). "Investigating whether anxiety-inducing events during wakefulness alter CRH dynamics during subsequent sleep could provide insights into how emotional experiences influence the neuromodulatory tone during NREMS and impact limbic adaptation during REMS." (PMID 40830097, 2025). "Moreover, the experience of pain and anxiety triggers the release of corticotropin-releasing hormone, subsequently activating the locus coeruleus, which releases noradrenaline for the rapid activation of sympathetic fibres." (PMID 40572646, 2025). "We investigated the correlations between six neurochemical markers (serotonin, AVP, CRH, corticosterone, testosterone, and oxytocin) and anxiety-like behaviour in the OFP and EPM, as well as aggressive behaviours in the resident intruder paradigm conducted pre and post the SxAT paradigm." (PMID 40011829, 2025). "Neuropsychiatric symptoms, such as anxiety, depression, anorexia, and insomnia, have also been reported and may be related to CRH excess." (PMID 39850725, 2025). "Mice with an overexpression of the 5-HT2C receptor exhibit increased anxiety-like behavior, while mice with 5-HT2C receptor absence show reduced responses to anxiety stimuli and suppressed anxiety-induced activation of corticotropin-releasing hormone (CRH) neurons." (PMID 40072112, 2025). "OT counters CRH-driven anxiety by reducing amygdala activity and enhancing vagal tone." (PMID 40864786, 2025). "Therefore, the excessive secretion of PVN CRH, causing HPA axis hyperactivity, deserves attention due to its role in inducing anxiety and adverse consequences following surgical trauma." (PMID 39153974, 2024). "Our results indicate that cocaine exposure can inhibit the firing rate of CRH neurons, and thus may exert effects on anxiety and addiction." (PMID 38681523, 2024). "Reportedly, anxiety was reduced in animal models of noise exposure due to changes in the mRNA expression of the corticotropin-releasing hormone (CRH) system, a stress hormone in the brain; however, the mechanism remains unclear." (PMID 39456767, 2024). "We found 5 min optogenetic activation of CRH-ChR2-mCherry mice significantly increased travel distance in the central area exploration time and center zone entries compared with CRH-Cre mice, indicating hyperactivity and decreased basal anxiety level." (PMID 38980648, 2024). "Moreover, CGRP, acting through its receptor complex in the bed nucleus of the stria terminalis (BNST), interacted with CRH and activated MCs through a CRH-R1-dependent mechanism, thereby contributing to anxiety." (PMID 38630738, 2024).